VHL (von Hippel-Lindau tumor suppressor)
Diseases named in the same sentence as VHL in open-access papers (continued):
Sharing a sentence is not in itself a finding about the gene and the disease.
tumor (continued). "Recent research in VHL has explored the use of MRI features to phenotype ccRCC, predict growth, and assess grade, but its utility in assessing tumour heterogeneity remains unexplored." (PMID 41241877, 2025). "Von Hippel-Lindau (VHL) is an E3 ligase that functions primarily as a tumor suppressor gene and plays a crucial role in cancer prevention." (PMID 41030787, 2025). "Restoration of VHL reprograms the tumor microenvironment, reducing ccRCC progression and immunosuppressive signaling while enhancing NK cell infiltration and activation." (PMID 40736709, 2025). "ccRCC is often characterized by inactivating mutations in the VHL gene, which lead to HIFα-mediated VEGFA production and the development of highly vascularized tumours." (PMID 40435846, 2025). "Under normoxic conditions, HIF-1α is tightly controlled by VHL protein, a tumor suppressor that acts as part of an E3 ubiquitin ligase complex." (PMID 41462905, 2025). "Together, our findings reveal a novel VHL-related pathway which can be therapeutically targeted to inhibit ccRCC tumor development." (PMID 40240354, 2025). "Loss-of-function mutations in VHL lead to unchecked HIF activation, promoting abnormal vascular proliferation and tumor development." (PMID 40649858, 2025). "A higher frequency of HIF1α-positive tumor-infiltrating NK cells were observed in VHL mutant RCC tumor spheroids compared with VHL-restored RCC tumor spheroids." (PMID 40736709, 2025). "Tumor morphology, volume, and weight measurements confirmed that Curcumol effectively inhibited tumor growth, while VHL knockdown promoted tumor progression and reversed the inhibitory effects of Curcumol." (PMID 41008845, 2025). "Somatic profiles and tumor pathology evaluations indicated that, in most cases, these somatic VHL alterations were passenger alterations due to genomic instability, and not the driver events in the development of tumors associated with the VHL gene." (PMID 40647474, 2025). "Upon inhibition of HIF1α in NK cells, an increased infiltration was observed in VHL mutant 786-O RCC tumor spheroids." (PMID 40736709, 2025). "In many cancers, VHL gene mutations or deletions result in loss of VHL function, leading to HIF-1α accumulation and tumor progression." (PMID 41446875, 2025). "In this study, we identify the von Hippel–Lindau (VHL) tumor suppressor as a novel E3 ubiquitin ligase that specifically targets Vpx for proteasomal degradation." (PMID 40522994, 2025). "CXCR4 is a hypoxia- and hypoxia-inducible factor (HIF)-induced receptor for the chemokine CXCL12/stromal cell-derived factor-1 (SDF-1), and is therefore a good marker for VHL mutant tumor cells." (PMID 39920694, 2025). "The VHL gene, a tumor suppressor gene, is one of the upstream regulators in the HIF signaling pathway." (PMID 40649858, 2025). "VHL mutation drives angiogenesis and immune suppression through hypoxia‐inducible factor (HIF) pathway activation, while KDM5C mutation promote tumor invasiveness via epigenetic dysregulation." (PMID 40539890, 2025). "Biologically, epithelial-mesenchymal transition (EMT) and phenotypic plasticity reduce affinity-capture yields, EV populations display high heterogeneity, and the VHL-hypoxia pathway drives extensive spatial and temporal tumor heterogeneity." (PMID 41479787, 2025). "The primary role of VHL is as a tumor suppressor which can lead to degradation of HIFs, primarily HIF-1α and HIF-2α." (PMID 39834300, 2025). "Numerous studies have demonstrated the efficacy of VHL in cancer treatment, with recent findings highlighting its anti-tumor activity across various malignancies, including renal cell carcinoma and ovarian cancer." (PMID 41030787, 2025). "VHL has been shown to function as a tumor suppressor across multiple tumor types through its role as an E3 ligase." (PMID 40255077, 2025). "This dual regulatory mechanism not only perpetuates HIF2α signalling but also provides a molecular basis for the limited efficacy of sunitinib in VHL-mutant tumours." (PMID 40435846, 2025).
tumor (continued). "In ccRCC, the loss of VHL leads to the accumulation of hypoxia-inducible factor (HIF) protein, which activates signaling pathways that promote tumor progression." (PMID 40361322, 2025). "The VHL tumor suppressor gene, identified in 1993, is essential for cellular oxygen sensing by targeting hypoxia-inducible factors." (PMID 40000790, 2025). "When the VHL gene is functional, its expression prevents excessive angiogenesis, thereby inhibiting tumor growth." (PMID 40005423, 2025). "When VHL is mutated or inactivated, HIF accumulates and drives the transcriptional upregulation of VEGF and other pro-angiogenic factors, thereby promoting tumor vascularization and progression." (PMID 40839124, 2025). "The VHL mutation, a hallmark of clear cell RCC, is known to contribute to tumor invasion of vascular structures, potentially explaining this unusual metastatic pattern." (PMID 40600205, 2025). "RBX1 is a component of the VHL tumor suppressor complex, which ubiquitinates HIFα subunits (HIF1α, HIF2α, and HIF3α) and targets them for degradation under normoxic conditions." (PMID 40436847, 2025). "LOH is a common mechanism of tumor suppressor inactivation, and the relevant region on chromosome 3 contains several tumor suppressor genes, including VHL, XPC, and MLH1." (PMID 41279090, 2025). "VHL is a recognized tumor suppressor, particularly in sporadic clear cell renal cell carcinomas (ccRCCs), where ∼91% of VHL mutations are found." (PMID 39050705, 2024). "The tumor selectivity of the PROTAC DT2216 is likely achieved from the minimal expression levels of the VHL E3 ligase in platelets, preventing them from undergoing apoptosis." (PMID 39000337, 2024). "This suppressive phenotype, however, is not present in all ccRCC cell lines, as knockout of ANGPTL4 or inhibition by treatment with anti-cANGPTL4 inhibits tumor growth in the 786O tumor model, a model with mutant VHL." (PMID 39105498, 2024). "Our finding that FIH loss alone can boost anti-tumour immunotherapy is in agreement with our own prior work on overexpression of HIF1 and HIF2 isoforms with differential sensitivity to FIH and VHL control." (PMID 38690263, 2024). "To further reinforce the link between ciliation and the VHL status, we reverted to clinical ccRCC tumor samples." (PMID 39389955, 2024). "T47D tumor growth was significantly increased when VHL was depleted, and this augmented tumor growth was effectively attenuated by UBE3B ablation." (PMID 38914543, 2024). "In clear cell renal cell carcinoma (ccRCC), FTO inhibits the presence and expression of von Hippel-Lindau (VHL) tumor suppressors, which limit tumor progression and progression by inhibiting FTO." (PMID 39033180, 2024). "The significance of VHL regulation on m6A and mRNA stability regulation lies in its role as a critical tumor suppressor in ccRCC and its ability to modulate key cellular processes involved in gene expression control." (PMID 38618952, 2024). "It is characterized by the loss of the short arm of chromosome 3 (3p) which harbors the VHL tumor suppressor gene, whose function is to regulate the hypoxia inducible factor (HIF) protein." (PMID 38666933, 2024). "Secondary to VHL, additional mutations (most notably in PBRM1, BAP1, and SETD2) enlist a large number of genetic and epigenetic events to drive advanced tumor evolution." (PMID 38618956, 2024). "Taken together, these results strongly indicated that VHL plays a crucial role in enabling MZ1 to exert its anti-tumor effect in GBM cells." (PMID 38365636, 2024). "Loss of the VHL gene, a common finding in ccRCC, interferes with TGF-β1 signaling consequently impairing its tumor-suppressive actions." (PMID 39813754, 2024). "Beclin1 P54A knock-in expression disrupted the binding of VHL to Beclin1 and VHL-mediated autophagy inhibition, largely abolished the tumor-suppressing effect of VHL, promoted tumor growth in mice." (PMID 38360997, 2024).
tumor (continued). "This includes the activation of tumor promoter genes (such as MAGE and S100P) and the silencing of tumor suppressor genes (such as VHL and MLH1) in a variety of cancers." (PMID 38510251, 2024). "The most common gene alterations in the primary tumor in RCC are VHL (64%), PBRM1 (36%), SETD2 (20%), and BAP1 (13%)." (PMID 38386122, 2024). "Tumor samples were further divided into the MAML, SDH, and VHL subtypes, which have distinct driver mutations." (PMID 38685127, 2024). "The Dutch and International criteria require one VHL-related tumor and a first- or second-degree relative diagnosed with VHL or with more than one VHL-related tumor." (PMID 38541874, 2024). "Recent research has revealed that the product of the von Hippel–Lindau (VHL) tumor suppressor gene, which is deactivated in VHL disease and sporadic clear cell renal carcinomas, targets the transcription elongation complex known as elongin." (PMID 39201746, 2024). "In 1988, a report explained the linkage of the VHL gene to chromosome 3, and, in 1993, a research group identified the VHL tumor suppressor gene." (PMID 39272694, 2024). "TKIs are the preferred targeted therapy that inhibits tumor growth and spread by targeting the von Hippel-Lindau (VHL) gene through vascular endothelial growth factor receptors." (PMID 39239550, 2024). "For example, the loss of the 3p chromosome arm disrupts critical genes like VHL, PBRM-1, BRCA1, and MTOR that act as tumor suppressors." (PMID 39796121, 2024). "The effects of Beclin1-mediated autophagy on tumor growth appear to depend on tumor stages and specific activation of oncogene or inactivation of tumor suppressor, such as VHL, in a cellular context-dependent manner." (PMID 38360997, 2024). "However, given that patients are susceptible to tumor development throughout their lives, having a predictive outlook on the onset of VHL-related cancers could allow clinicians to devise a more personalized surveillance strategy when presented with a unique mutation." (PMID 39138406, 2024). "The panel NGS of the primary tumor revealed pathogenic mutations in PBRM1 and PTEN and likely pathogenic mutations in VHL as well as PIK3C2G." (PMID 38611655, 2024). "We also know from a recent report that miR-155 has a significant function in promoting tumor angiogenesis by inducing the downregulation of von Hippel-Lindau (VHL)." (PMID 38394221, 2024). "This is because VHL is minimally expressed in platelets, limiting the effect on platelets and leading to selective killing of tumor cells." (PMID 38534371, 2024). "Our results, therefore, suggest that VHL loss significantly attenuated tumor growth and made them more susceptible to ICB therapy in multiple murine tumor models." (PMID 39050705, 2024). "ccRCC is associated closely with mutations in the VHL gene that lead to the activation of HIF-1α and HIF-2α via a pseudohypoxia mechanism, resulting in the transcription of genes involved in tumor progression." (PMID 39399506, 2024). "Suppression of HIF2α is required for VHL to inhibit ccRCC tumor growth 13,14, highlighting the oncogenic role of HIF2α in ccRCC." (PMID 39070610, 2024). "The VHL protein reduces tumor formation via modification of multiple chemical signaling pathways, the most well studied of which being its role in HIF-1α regulation." (PMID 37883464, 2024). "In-silico analysis also showed that LINC01322 can be involved in RCC progression by interacting with VHL that regulates tumor microenvironment." (PMID 39886373, 2024).
tumor (continued). "Other genes such as APC, KRAS, VHL and IDH1 were highly enriched for mutations in only one or two tumor types." (PMID 38200255, 2024). "Utilising pooled genome-wide CRISPR/Cas9 mutagenesis in ccRCC cell lines, we uncover synthetic lethal interactions for VHL, and find that Core Binding Factor β (CBF-β) loss selectively results in decreased tumour growth in ccRCCs." (PMID 39282259, 2024). "In contrast, these PROTACs can efficiently degrade BCL-xL in tumor cells, which possess significantly high levels of VHL compared to platelets." (PMID 38534371, 2024). "VHL is a tumor suppressor, acting as a substrate adaptor, consisting of the VHL E3 ubiquitin ligase complex together with Cullin-2 (Cul-2), Elongins B/C (ELB/ELC), and RING-box." (PMID 39748950, 2024). "ccRCC is identified as a highly angiogenic tumor characterized by alterations in the VHL gene and increased expression of VEGF-A compared to other tumor types." (PMID 38791528, 2024). "Some studies suggest significant differences in the transcriptome profiles between VHL-mutant cells and their primary tumor samples." (PMID 39600908, 2024). "This “two-hit” model proposed by Knudson has been fundamental in understanding tumor progression in VHL and has led to deeper investigations into the molecular mechanisms involved in this disease." (PMID 39272694, 2024). "In this retrospective, claims-based study, both VHL-CNS-Hb and VHL-pNET were associated with substantial HRU and healthcare costs, particularly tumor reduction surgery–related costs." (PMID 38365728, 2024). "•In-silico analysis also revealed that LINC01322 regulated tumor microenvironment during RCC progression by interacting with VHL." (PMID 39886373, 2024). "HIF‐1α was stabilized as a result of VHL inactivation and it was strictly associated to RCC, therefore, HIF‐1α expression was observed only in tumor organoids." (PMID 38923304, 2024). "Then these tumor samples and adjacent normal tissues underwent immunohistochemistry (IHC) staining with antibody for VHL and immunofluorescence (IF) staining with cilia marker Arl13b." (PMID 39389955, 2024). "Targeting the PI3K/Akt/mTOR pathways is a promising strategy in cancer, and possible in VHL treatment due to their central role in tumor biology, potential to overcome resistance, and ability to enhance the effectiveness of existing therapies." (PMID 39272694, 2024). "On another note, a positive correlation was reported between heightened AR levels and increased expression of the VHL tumor suppressor, hinting at an alternative mediator through which AR acts." (PMID 39585048, 2024). "Beclin1 P54A knock-in expression abrogates VHL-mediated autophagy inhibition and promotes tumor growth." (PMID 38360997, 2024). "Of note, deletions in chromosome 3p tended to be a universal truncal event in ccRCC, as this region contains the VHL tumor suppressor locus." (PMID 38216635, 2024). "On the other hand, VHL-related tumor development follows Knudson’s ‘two-hit model’ of tumorigenesis: Patients with VHL are born with a germline mutation in one copy of their VHL gene in all cells (first hit or event)." (PMID 39272694, 2024). "On the other hand, in cancer therapy directed against HIF-1α and VHL, it shows important effects, decreasing tumor growth and cancer progression." (PMID 38921041, 2024). "786O cells were established from a ccRCC tumor biopsy in which VHL is inactive, resulting in constitutive stabilization of endogenous wildtype HIF2α." (PMID 39070610, 2024). "VHL pathway activation: The level of HIF-1α can be reduced by deactivating the VHL tumor suppressor pathway." (PMID 39493156, 2024). "Each varies slightly in what they utilize for a family history of VHL or a related tumor and individual diagnosis of a VHL-related manifestation." (PMID 38541874, 2024). "Mechanistically, the VHL-m6A–regulated PIK3R3 suppresses tumor growth by restraining PI3K/AKT activity." (PMID 38618952, 2024).
tumor (continued). "One caveat related to the NR-V04 is the usage of VHL, which is a well-established tumor suppressor gene and very commonly mutated in human cancers such as RCCs." (PMID 38334978, 2024). "VHL is a tumor suppressor that plays pleiotropic roles in cells, including targeted protein degradation, ciliogenesis, extracellular matrix assembly, proliferation, survival, migration and cell polarity." (PMID 39334449, 2024). "The VHL tumor-suppressor gene mediates and participates in the transduction of the hypoxia signaling pathway through HIFα." (PMID 38928435, 2024). "The VHL gene is positioned on the 3q25-26 region of the human chromosome and is a well-established tumor suppressor gene." (PMID 38481814, 2024). "For instance, in clear cell renal cell carcinoma, inactivation of VHL can trigger histone lactylation, activating the PDGFRβ signaling pathway, forming a positive feedback loop, and promoting tumor progression." (PMID 39010066, 2024). "The HIF/VHL pathway regulates interferon-γ (IFN-γ) expression in T helper cell type 1 (Th1) immunity during both tumor growth and autoimmune cascades." (PMID 36611440, 2023). "Particularly, in the case of VHL disease, we have published the case of a 76-year-old woman in which a mutation in CLN5 (ceroid lipofuscinosis, neuronal, 5) offers a protective effect, preventing VHL-related tumour development." (PMID 37843608, 2023). "Von Hippel–Lindau (VHL) is a tumor suppressor that leads to the ubiquitination and destruction of hypoxia-inducible factor (HIF)1α and HIF2α (HIF1/2α) in normoxic conditions and is mutated in 64% of ccRCC cases." (PMID 37568390, 2023). "Collectively, the data from the VHL-deleted RCC models, #22, ACHN and RENCA, revealed that the cooperative interactions between two distinct populations of tumor cells (VHL− and VHL+ cells) are required to produce distant metastases." (PMID 37069149, 2023). "Von Hippel–Lindau (VHL) is a tumor suppressor gene and the substrate‐conferring component of the E3 ubiquitin ligase complex." (PMID 37563971, 2023). "In this study, our VHL-deleted RCC models reveal a novel metastatic mechanism that relies on cooperative interactions between two distinct populations of tumor cells: VHL-KO (VHL−) and VHL-WT (VHL+) cells." (PMID 37069149, 2023). "The CAM PDXs established from small tumor pieces of the primary tumor from case #22 revealed the presence of intermixed VHL+ and VHL− tumor cells." (PMID 37069149, 2023). "Another effect caused by the inactivation of the VHL gene is the increase in VEGF concentration, which induces tumor angiogenesis." (PMID 37370817, 2023). "IHC of the lung metastases of case #22 showed a high prevalence of VHL+ cells, far exceeding the 40% VHL positivity in the primary tumor." (PMID 37069149, 2023). "In this study we assessed the effects of VHL polymorphisms on patients’ gender and age, tumor size, WHO/ISUP grade, and AJCC TNM pathologic primary tumor stage (pT)." (PMID 38115281, 2023). "The interplay between VHL+ and VHL- cells results in increased tumor aggressiveness, whereas tumors with only VHL- or VHL+ cells have minimal metastatic potential." (PMID 37887570, 2023). "The VHL tumor suppressor gene is located on the short arm of chromosome 3 mapped to 3p25-3p26 and comprises 639 nucleotides in 3 exons encoding 213 amino acids." (PMID 36835190, 2023). "In human cancers harboring wild-type VHL, the aberrant downregulation of pVHL is frequently detected and critically contributes to tumor progression." (PMID 36813923, 2023). "The VHL protein (pVHL) functions as a tumor suppressor by regulating the degradation or activation of protein substrates such as HIF1α and Akt." (PMID 36813923, 2023). "Consistently, results of xenograft experiments showed that ATRA inhibited tumor growth and increased the sensitivity to cisplatin, which was largely abrogated by the depletion of VHL." (PMID 36813923, 2023).